IFI44 (interferon induced protein 44)
Diseases named in the same sentence as IFI44 in open-access papers (continued):
Sharing a sentence is not in itself a finding about the gene and the disease.
infection (65 papers, 2011 to 2026). The state of being infected such as from the introduction of a foreign agent such as serum, vaccine, antigenic substance or organism. "We demonstrate, for the first time, that the loss of IFI44 expression in a mouse model of infection is associated with more severe RSV disease." (PMID 32611756, 2020). "IFI44 multigene family are interferon-alfa inducible proteins, which are associated with infection of several viruses and can affect viral replication." (PMID 31959106, 2020). "The loss of Ifi44 was associated with a more severe infection phenotype in a mouse model of infection." (PMID 32611756, 2020). "For instance, we observed that the genes encoding interferon induced protein 44 (Ifi44 gene) and schlafen family member 12 like (Slfn12l gene) are two of the most highly induced genes in Muc1−/− mice vs. WT at 24 h post-infection." (PMID 32793510, 2020). "One of the most interesting features of infection of Raji cells with XMLV was the up-regulation of the IFI44 and IFI44L genes that have been implicated as interferon-stimulated genes that confer resistance to HCV in vitro." (PMID 25912714, 2015). "IFI44 is an interferon-alpha inducible protein associated with infection by several viruses." (PMID 36911395, 2023). "IFI44 is an interferon-alpha inducible protein associated with infection of several viruses." (PMID 28098800, 2017). "Overexpression of IFI44 or IFI44L was shown to restrict RSV infection at an early time point after infection, whereas knockout of these genes in mammalian airway epithelial cells resulted in increased levels of RSV titer." (PMID 38896252, 2024). "In addition, IFI44 was totally silenced upon 85-7 strain infection, but it was extremely activated in the variant 85-7C40 infection process, further illustrating that the PEDV 85-7 strain might shield the expression of numerous anti-PEDV ISGs to create an enabling environment in a specific manner." (PMID 35762780, 2022). "IFI44, ISG15, MX1, RSAD2, SAMD9 and TNFSF10 were chosen as they are infection-associated genes that show lower expression levels in Holstein infected cells compared to Sahiwal cells." (PMID 35061738, 2022). "To evaluate type I interferon responses earlier in infection, we examined the abundance of interferon-induced protein 44 (IFI44) and OAS-3 at 6 and 9 dpi by qPCR." (PMID 34928716, 2022). "Genes encoding interferons (Ifnb, Ifnl2 and Ifnl3), chemokines (Ccl7, Ccl5, and Cxcl10), and ISGs (Ifit1, Ifit2, Ifit3b, Oas3, Ifi44, Rsad2, and Isg15, among others) were prominently represented among those induced by infection in Ifnar1-/- mice." (PMID 34591933, 2021). "Knocking out these genes in human cells increases levels of infection, thus demonstrating a function for IFI44 and IFI44L in controlling RSV infection." (PMID 33968942, 2021). "In vivo, the expression of both Ifi44 and Ifi44l RNA was significantly upregulated rapidly after intranasal infection of BALB/c mice, detectable from 6 h (P < 0.05)." (PMID 32611756, 2020). "We observed that Ifi44−/−/Ifi44L−/− mice infected with RSV had higher levels of viral RNA present in their lungs at the peak of infection, along with decreased expression of the proinflammatory factor interleukin-1β (IL-1β)." (PMID 32611756, 2020). "In this work, we describe a completely novel role for IFI44 in negatively regulating innate immune responses induced by infection with different viruses, including IAV, VSV, SeV, and LCMV." (PMID 31455651, 2019). "Nevertheless, several downstream genes of the type I IFN signaling pathway were elevated, consistent with reports of other New World arenavirus human infection, including Ifi27, Ifi27l2b, Ifi44, Ifi204, Ifit1, Mx1 and Mx2." (PMID 29724035, 2018). "ML29 down-regulation of IFI44 probably allows the virus to replicate early during the infection so that a strong immune response can control viral replication and spreading." (PMID 24069471, 2013).
infection (continued). "Additionally, compared to AFG3L2-deficient cells, cells reconstituted with wild-type AFG3L2 but not the protease-inactive AFG3L2E575Q mutant inhibited SeV-induced transcription of IFNB1 and IFI44 genes at 8 h post-infection." (PMID 41599057, 2026). "By 72 h post-infection, although only five common genes (IFI44, OASL, OAS3, IRF9, IRF7) are identified, these genes contribute significantly to a range of crucial GO processes, emphasizing the depth of the immune response despite the limited number of genes involved." (PMID 38957806, 2024). "Numerous ISGs activated by 85-7C40 showed antiviral effects against the wild-type strain infection, particularly the IFI44 (an ISG upregulated specifically by the 85-7C40 infection) and OASL (upregulated higher in 85-7C40 than 85-7-infected cells), exhibited powerful antiviral activity." (PMID 35762780, 2022). "Furthermore, all identified infection-associated ISG genes (MX1, MX2, OAS1Y/Z, OAS2, ISG15, IFI6, IFI44 and RSAD2) showed lower expression values in Holstein infected cells relative to Sahiwal." (PMID 35061738, 2022). "Indeed, overexpression of IFI44 or IFI44L is sufficient to restrict RSV infection at an early time post-infection." (PMID 33968942, 2021). "Interestingly, we observed a decrease in ISG expression in brachial lymph nodes of xeno mice 2 days following infection, with Ifi44, Irf7, and Stat2 mRNA levels reduced." (PMID 33031404, 2020). "In contrast, untreated infection networks were dominated by inflammatory mediators (IL6, CXCL10, CCL2, VCAM1, SELE) and antiviral sensors (DDX58, OAS1, IFI44, IFI6), which reflect strong cytokine and interferon-driven immunity." (PMID 41480150, 2025). "The observed upregulation of Mx1, Ifi44, and Sting1 is indicative of type I interferon (IFN-I) pathway activation, often triggered by cellular stress, infection, or cytosolic self-derived mitochondrial DNA (mtDNA)." (PMID 41465333, 2025). "While the number of significantly upregulated genes decreases to 37, these genes (e.g., ISG15, IFI6, IFI44L, HP, OAS1, IFI44, OASL, and IFI27) likely play a crucial role in the response to the progressing infection." (PMID 39282474, 2024). "qRT-PCR assay showed that eight antiviral-related mRNA including IRF3, IRF7, IKKβ, TBK1, IFIT1, IFI44, MX1 and ISG15 displayed significantly stronger and quicker response at early infection under 20 °C." (PMID 37627029, 2023). "The previous research reported that IFIT1, IFIT2, IFTI3, IFIT3, IFI44, HERC4, and OASL genes are antitumoral effects and modulated the inflammatory response in cancer and infection." (PMID 35941292, 2022). "The expression of TRIM21, MDA5, cGAS, LGP2, and IFI44 was increased and the expression of RAS, GLOM2, HSP, FOX and TLCD4B was decreased in the foregut following SVCV infection." (PMID 36330521, 2022). "Induction of the IFN I pathway after infection with the wt isolate was evident by up-regulation of several interferon-induced proteins, i.e., IFIT-I, ISG15, IFI44, GIG1, interferon-induced very large GTPase 1, IRF3, IRF7, and Mx." (PMID 35215144, 2022). "Infection of HEp2 cells overexpressing IFIT1–3 or IFI44 individually with RSV, showed that the multiplicity rate of RSV was inhibited starting from 72 h post-infection (p < 0.01)." (PMID 33081322, 2020). "We show that very early in infection, HIV-1 suppresses peripheral type I interferon (IFN) and interferon-stimulated gene (ISG) responses, including the HIV-1 restriction factor IFI44." (PMID 30867315, 2019). "IFI44 is an ISG and is induced after infection with different viruses such as rhinovirus and papillomavirus." (PMID 31455651, 2019). "IFI44 is a type I IFN-induced protein and is upregulated after infection with different viruses, such as SeV, LCMV, VSV, and IAV." (PMID 31455651, 2019). "Thirty-nine viral genes and five host genes including MyD88, IFI44, IkB2, IAP and Gly were measured at 0.5, 10, 26, 72 and 144 hours post infection (hpi)." (PMID 25294338, 2014).
infection (continued). "With the insertion of K1L and C7L, this response was tempered; infection with NYVAC-C-KC-ΔB8RΔB19R induced increased transcriptional levels of seven of the genes shown, relative to NYVAC-C-KC (IFI35, IFI44, IFI44L, IFIT1, IFIT3, IFITM1, and IFITM2)." (PMID 22096477, 2011). "The 17 DEGs upregulated after infection with huH1N1 were shared with the swH1N1 infection (DDX58 (RIG-I), RSAD2 (Viperin), MX2, MX1, OAS1, ANGPTL4, IRF7, ISG15, IFIT1, ISG12(A), DDX60, BST2, IFI44, XAF1, LGALS3BP, RTP4, and IFI6)." (PMID 39247193, 2024). "Furthermore, the temporal expression profiles of eight selected antiviral-related mRNA including IRF3, IRF7, IKKβ, TBK1, IFIT1, IFI44, MX1 and ISG15 were detected by qRT-PCR, which showed a significantly stronger response at early infection under 20 °C." (PMID 37627029, 2023). "Overexpression of IFI44 has been shown to restrict Bunyamwera virus and HIV-1 infection." (PMID 33968942, 2021). "Moreover, similar expression levels for several Interferon-stimulated genes (ISGs), namely Ifit1, Ifi44, Usp18, Ifit3 and Irf7, were observed in the livers of Ctrl and RKV-supplemented mice at various time points after infection." (PMID 33294789, 2020). "IFI44 is also an ISG and its expression is induced following infection with different viruses." (PMID 33081322, 2020). "Induction of the IFN I pathway after infection with the wt isolate was also evidenced by the upregulation of several interferon-induced proteins (IFIT-I, ISG15, and IFI44) in head kidney and nervous tissue, and some exclusively in head kidney (GIG1 and interferon-induced very large GTPase 1)." (PMID 30065724, 2018). "Expression of the interferon‐stimulated genes (ISGs) Ifit1, Ifi44 and Oasl1 was increased upon infection and was not altered in cells expressing ZBP1." (PMID 28716805, 2017). "Higher IFNβ and IFI44 levels were not due to increased infection rates." (PMID 28859166, 2017). "Nevertheless, during infection with the PTG strain, we identified two loci, Ifi44-lnc and Socs2, that were not expressed in the microarray but did appear to be regulated in the qRT-PCR." (PMID 30301916, 2018).
tumor (29 papers, 2009 to 2026). "We observed that IFI44 was markedly elevated in ccRCC tissues, and its increased level was closely associated with advanced tumor stage and poorer patient survival." (PMID 41799288, 2026). "IFI44 was reported to negatively regulate innate immune and antiviral responses; it is also implicated in immune infiltration in the tumor microenvironment." (PMID 35449555, 2022). "Further, the expression of IFI44 was associated with the portions of neutrophils and M0, M1, and M2 macrophages in the tumor section." (PMID 33123469, 2020). "In addition, immune infiltration associated with IFI44 mRNA expression was explored through Tumor IMmune Estimation Resource (TIMER) and Estimation of STromal and Immune cells in MAlignant Tumors using Expression data (ESTIMATE) databases." (PMID 33123469, 2020). "Moreover, elevated IFI44 expression may be associated with an immunosuppressive tumor microenvironment, as suggested by increased infiltration of effector T cells and M1 macrophages, along with decreased infiltration of activated dendritic cells." (PMID 41799288, 2026). "We found that THP1-derived macrophages (THP1-MΦ) cocultured with IFN-β–treated USP5-deficient tumor cells exhibited upregulated ISG15, IFI44, CXCL9, and CXCL10 mRNA expression." (PMID 41321309, 2025). "FLOR2 is down-regulated in resistant tumors, suggesting an increased inflammatory tumor microenvironment, which is consistent with the effect of increased IFI44 gene expression in resistant tumors." (PMID 39001376, 2024). "TCGA database analysis revealed that LOX and IFI44 mRNA expressions were higher in ESCA tumor tissues, while IL18 and SLURP1 mRNA expressions were higher in normal tissues." (PMID 36090891, 2022). "The potential role of IFI44 in tumor formation and development needs further experimental verification." (PMID 34136486, 2021). "To identify the underlying mechanisms of IFI44 involved in HNSC, we selected the top 100 genes from HNSC tumor samples and normal tissues through the GEPIA database, among which 60 genes were distinctly expressed in HNSC." (PMID 33123469, 2020). "Higher expression of IFI44 was detected in the tumor section than normal tissues both at mRNA and protein levels." (PMID 33123469, 2020). "As an important immune-related gene, IFI44’s potential value in tumor formation and progression is worthwhile to be disclosed." (PMID 33123469, 2020). "Among these genes, there was few studies reported that OAS1 and IFI44 were related to tumor progression." (PMID 32241279, 2020). "To verify that IFI44 was closely related to the infiltration of CD4+ T lymphocytes in the tumor area, we then explored the relationship between 66 core genes and CD4+/CD8+ cells using TIMER database." (PMID 33123469, 2020). "Results above revealed that IFI44 was closely correlated with related mechanisms regarding tumor formation and progression." (PMID 33123469, 2020). "With the significant prognostic roles of IFI44 in HNSC, multiple analyses were performed, including competing endogenous RNA (ceRNA) network, methylation, copy number count and tumor mutation burden." (PMID 33123469, 2020). "Our initial exploration demonstrated that IFI44 perhaps closely correlated with immune infiltration in the tumor microenvironment (TME), which contributed a lot to the tumorigenesis and development of HNSC." (PMID 33123469, 2020). "Taken together, these data suggested that IFI44 was abnormally expressed in cancer tissues and indicated the potential impact of IFI44 on the tumor immune infiltration in HNSC." (PMID 33123469, 2020). "Using the gene set uniquely co-expressed with IFI44 in HNSC tumor samples, we conducted GO and KEGG pathways analyses via DAVID database." (PMID 33123469, 2020). "Expression of IFI44 in GSE8835 was associated with the amount of CD4+ cells and CD8+ cells infiltrating in the tumor section, and 66 genes were distinguished as enriched immune signature genes in IFI44-high expression group in HNSC." (PMID 33123469, 2020).
tumor (continued). "The Kyoto Encyclopedia of Genes and Genomes (KEGG) and Gene Ontology (GO) results showed that IFI44 was correlated with tumor formation and progression." (PMID 33123469, 2020). "Here, we detected the expression of IFI44 in The Cancer Genome Atlas (TCGA) Pan-cancer and generally explored the effect of IFI44 on immune infiltration in the tumor microenvironment (TME)." (PMID 33123469, 2020). "This study provides original knowledge that IFI44 plays a pivotal role in tumor immune infiltration and has a predictive value in the prognosis of HNSC patients." (PMID 33123469, 2020). "In summary, the data show that IFI44 acts as an oncogene in ccRCC, promoting tumor progression through its interaction with PRDX1 while also shaping an immunosuppressive microenvironment, and suggest that IFI44 is a promising biomarker of prognosis and candidate therapeutic target for ccRCC." (PMID 41799288, 2026). "In the analysis between the tumour tissues, mRNAs of LAMA3, E2F7, and IFI44 were more expressed in the tissues of the high-risk group than in those of low-risk group, whereas the expression levels of IFI44 and LRIG1 were lower in the high-risk group than in low-risk group." (PMID 31703415, 2019). "For evaluating the role of PTEN expression on cGAS-STING activity and tumour immunogenicity, mRNA expression levels of interferon-stimulated genes, especially IFNB, IFIT2, IFI44, and IL6 were analysed." (PMID 38214828, 2024). "IFI44 is found on human chromosome 1p31.1 ad belongs to the interferon-stimulated gene (ISG), which plays a significant role in immunoregulation and tumor cell recognition." (PMID 36845395, 2023). "We first confirmed that tumor tissues with chemohormonal treatment showed a higher level of IFN-stimulated genes, such as IFIT1, IFI44, CCL5, and IFNB, compared with treatment-naive tissues." (PMID 35836810, 2022). "Results above concluded that IFI44 acted as an oncogene in HNSC and functioned heterogeneously in tumor formation and progression." (PMID 33123469, 2020). "Among the top genes differentially expressed between sensitive and resistant cells, we identified a group of candidates related to tumor-microenvironment response (CCL5, CXCL10, IFIT3, IFI44, IFNL2)." (PMID 32365528, 2020). "The up-regulated CEP55, IFI44, NCF4, and TCIRG1 with HR > 1 were regarded as oncogenes and were proved to be closely related to tumor progression by using comprehensive bioinformatics analysis." (PMID 33101364, 2020). "IFI44 is situated on human chromosome 1p31.1 and is part of the interferon-stimulated gene (ISG) family, which has a crucial function in regulating immunity and recognizing tumor cells." (PMID 38162574, 2023). "Likewise, interferon response genes (including TLR3, MX1, RSAD2, IFI44, IFI27, IFIT1, and IFIT3), and chemokine genes (including CCL7, CXCL10, CXCR1, and CCL25) were significantly increased in PM-treated MM tumor tissues, whereas panobinostat showed minimal effects at equivalent doses." (PMID 40562746, 2025). "Moreover, qRT-PCR verified seven apoptosis-related genes (APP, DOCK8, IFI44, MDK, SLC27A2, TNFAIP2, WNT5A) with at least 2 fold changes by means of 2−ΔΔCt method, finding that APP, SLC27A2 and WNT5A had a low expression, while DOCK8, IFI44, MDK, TNFAIP2 had a high expression in ccRCC tumor tissues." (PMID 33748185, 2021). "In new tumor occurrence after initial treatment of HNSC, IFI44 mRNA expression was found significantly higher than no recurrent cases." (PMID 33123469, 2020).